FREM3 (FRAS1 related extracellular matrix 3)
Description:
Extracellular matrix protein which may play a role in cell adhesion.
Tractability: Antibody: its Gene Ontology location is reachable by antibodies, with high confidence; UniProt places it where antibodies can reach, with medium confidence; UniProt predicts a signal peptide or a membrane-spanning region.
Gene: Protein-coding gene on chromosome 4 (143,577,302 to 143,700,675, reverse strand). Ensembl gene ENSG00000183090.
Subcellular location: Secreted, extracellular space, extracellular matrix
Gene Ontology:
Biological process: cell adhesion; cell-matrix adhesion; epithelial structure maintenance; cell communication
Cellular component: extracellular region; basement membrane; extracellular matrix; membrane
Genetic constraint (gnomAD): Loss-of-function variants: 94 observed, 119.48 expected, observed/expected ratio (o/e) 0.79, 90% interval 0.67 to 0.93. The upper end of that interval is the gene's LOEUF score, 0.93, which puts it in group 3 of 6, group 1 being the genes least tolerant of losing a copy. Missense variants: 2,475 observed, 2,622.2 expected, observed/expected ratio (o/e) 0.94, 90% interval 0.91 to 0.98. Synonymous variants: 978 observed, 1,029.1 expected, observed/expected ratio (o/e) 0.95, 90% interval 0.9 to 1.
Homologues: Orthologues: chimpanzee FREM3 (99% identical), macaque FREM3 (95% identical), guinea pig FREM3 (72% identical), mouse Frem3 (68% identical), rat Frem3 (68% identical), rabbit FREM3 (65% identical), tropical clawed frog frem3 (58% identical), zebrafish frem3 (57% identical). Paralogues in human: FREM2 (57% identical), FREM1 (28% identical), FRAS1 (28% identical), ADGRV1 (15% identical), SLC8A1 (8% identical), SLC8A2 (7% identical), SLC8A3 (7% identical).
Diseases named in the same sentence as FREM3 in open-access papers:
FREM3 is named in the same sentence as 12 diseases in open-access papers, as found by Europe PMC text mining. Sharing a sentence is not in itself a finding about the gene and the disease. The quoted sentences say what the papers report.
malaria (12 papers, 2015 to 2023). Malaria is a serious and sometimes fatal disease caused by a parasite that commonly infects a certain type of mosquito which feeds on humans. "People carrying one copy of FREM3 rs186873296 allele have a reduced risk of severe malaria by about 40%." (PMID 33981715, 2021). "In our extended sample set of severe malaria cases from Kenya, we found that the rs186873296 FREM3 polymorphism correlated closely with the polymorphism that is specific to Dantu." (PMID 30033078, 2018). "A haplotype analysis using the FREM3 SNPs (rs149914432, rs186790584, and rs186873296) revealed a 55% reduced risk of severe malaria between the 2 major haplotypes (OR for CTG vs AAA, 0.448; P = .003)." (PMID 25805752, 2015). "The most significant association—between severe malaria and FREM3 (rs149914432)—arose through a approximately 59% reduced risk of acidosis (OR for AC vs other genotypes, 0.411; P = .0057)." (PMID 25805752, 2015). "As for FREM3, it was identified as a selection or GWAS signal of malaria in African populations in previous studies, and the polymorphism of FREM3 was reported to be associated with differential susceptibility to severe malaria." (PMID 36173765, 2022). "ABO blood group, USP38, FREM3 and alpha-thalassemia have previously been putatively associated with severe malaria in a Tanzanian population, but these associations are no longer statistically significant (P>10−4) at a more stringent GWAS significance threshold." (PMID 29381699, 2018). "Several SNPs in FREM3 were associated with acidosis and severe malaria in our study." (PMID 25805752, 2015). "In the remaining genomic risk loci, the well-known genes that play role in severe malaria resistance including ATP2B4 (chr1q32), FREM3, GYPE, and GYPB (chr4p31) were replicated and few additional genes were identified." (PMID 34868193, 2021). "rs186873296 between FREM3 and GYPE was associated with similar levels of protection against all three major phenotypes of severe malaria and protected against inpatient mortality." (PMID 30033078, 2018). "Further polymorphisms associated with severe malaria were noted for rs1541255 in ATP2B4 (adjusted OR 0·76, 95% CI 0·63–0·92; p=0·001) and rs186873296 located in an intergenic region between FREM3 and GYPE (0·64, 0·53–0·79; p=3·18 × 10−14)." (PMID 30033078, 2018). "Further, balancing selection has been observed in autosomal malaria candidate regions like FREM3, the major histocompatibility complex, and the sickle cell trait loci." (PMID 25671784, 2015). "In 32 loci passing quality control procedures, we found polymorphisms in USP38, FREM3, SDC1, DDC, and LOC727982 genes to be putatively associated with differential susceptibility to severe malaria." (PMID 25805752, 2015). "FREM3 contains no pathogenic variant sites in our analysis but does contain variant sites associated with glycated haemoglobin levels and severe malaria as annotated in the GWAS catalog." (PMID 37736706, 2023). "Although FREM3 apparently is not correlated with malaria and COVID-19, a recent study has demonstrated a link between a variant of FREM3 (rs186873296) and malaria." (PMID 33981715, 2021). "Although previous studies have highlighted associations between polymorphisms in ATP2B4 and FREM3 and malaria risk, they have lacked detail about the precise clinical effects of these polymorphisms." (PMID 30033078, 2018). "Moreover, previous studies have not confirmed that the association between FREM3 and severe malaria is accounted for by close chromosomal linkage to the rare blood group antigen Dantu." (PMID 30033078, 2018). "Furthermore, rs186873296 FREM3 polymorphism correlates closely with the polymorphism that is specific to Dantu a hybrid gene comprising GYPA and GYPB, which encodes a blood antigen known as Dantu (Red blood cell tension protects against severe malaria in the Dantu blood group)." (PMID 33981715, 2021).
malaria (continued). "SNPs in USP38 have been associated with susceptibility to asthma, but the gene lies in a 700-kb region close to malaria candidates in the GYP-E/A/B gene cluster as well as the SMARCA5 and FREM3 loci." (PMID 25805752, 2015).
depression (2 papers, 2015 to 2023). "FREM3 is associated with depression and aging in human brain." (PMID 37221602, 2023). "Finally, we explored the possible involvement of FREM3 in depression risk by linking additional functional variation in the same gene (rs1391187) to behaviorally relevant differences in in vivo brain function." (PMID 26441752, 2015). "The A allele of the FRAS1-related extracellular matrix protein 3 (FREM3) rs7676614 single nucleotide polymorphism (SNP) was linked to major depressive disorder (MDD) in an early genome-wide association study (GWAS), and to symptoms of psychomotor retardation in a follow-up investigation." (PMID 26441752, 2015). "However, future studies should incorporate other ethnicities in order to more fully characterize the role of FREM3 on depression risk." (PMID 26441752, 2015). "Together, these results suggest common genetic variation associated with reduced FREM3 expression may confer risk for a subtype of depression characterized by reduced reactivity to environmental stimuli and slower perceptual processing speed, possibly suggestive of accelerated aging." (PMID 26441752, 2015). "In line with significant overlap between age- and depression-related molecular pathways, parallel work has shown that FREM3 expression in postmortem human brain decreases with age." (PMID 26441752, 2015). "Taken together, these data suggest that FREM3 functional variation may uniquely contribute to risk for a subtype of depression that is not precipitated by stress, but is rather a more proximal result of genetic influences." (PMID 26441752, 2015).
Fraser syndrome (2 papers, 2015 to 2023). Fraser syndrome is a rare clinical entity including as main characteristics cryptophthalmos and syndactyly. "This is supported by the fact that Frem3-deficient mice do not develop signs of Fraser syndrome, and a human disease due to FREM3 deficiency is not known." (PMID 37047755, 2023).
epilepsy (1 paper, 2020). A brain disorder characterized by episodes of abnormally increased neuronal discharge resulting in transient episodes of sensory or motor neurological dysfunction, or psychic dysfunction. "Finally, the Light Green Cluster highlighted the selective effect of epilepsy on upper-layer L2–3_Cux2_Lamp5 and L2–3_Cux2_Frem3 principal neurons that consist of dysregulated neuronal morphogenesis GO terms." (PMID 33028830, 2020).
glioma (1 paper, 2023). A benign or malignant brain and spinal cord tumor that arises from glial cells (astrocytes, oligodendrocytes, ependymal cells). "We subsequently found that ADAMTS20 and FREM3 were interrelated lower risk of glioma using Cox regression analysis, whereas LAMB4, MMP1, and MMP7 showed high risk of glioma." (PMID 37335645, 2023). "For the sake of clarifying the expression of BMGs in glioma, this study screened 9 BMGs that were upregulated in glioma (FBN2, FREM3, Lamb4, MEP1A, MMP1, MMP7, OPTC, EVA1A, and ADAMTS20) from TCGA -GTEX expression matrix." (PMID 37335645, 2023).
virus infection (1 paper, 2021). "GYPB rs6840234 decreases the expression of both glycophorin B and FREM3, and how this effect can protect against virus infection remains to be elucidated." (PMID 33981715, 2021).
α-thalassemia (1 paper, 2015). "The new candidates accounted for the remaining 19.2% of the explainable variation, with USP38 (8.1%), DDC (3.8%), FREM3 (3.0%), SDC1 (2.6%), and LOC727982 (1.7%) all accounting for more variation than ABO blood group and α-thalassemia but in aggregate less than the sickle HbAS polymorphism." (PMID 25805752, 2015).
FREM3 also shares sentences with these, for which no sentence is quoted: Alpha-thalassemia (1 paper); asthma (1); COVID-19 (1); oligodendroglioma (1); sickle cell disease (1).